IL1B (interleukin 1 beta)
Diseases named in the same sentence as IL1B in open-access papers (continued):
Sharing a sentence is not in itself a finding about the gene and the disease.
Stroke (continued). "MMP-2 is up-regulated in EC exposed to inflammatory cytokines such as interleukin-1-beta and growth factors including nerve growth factor, where in vivo, it promotes capillary invasion and so is probably increased in active stroke regions undergoing remodelling." (PMID 19292924, 2009). "We therefore set out primarily to examine (a) whether circulating IL-1ra is elevated and related to stroke severity or outcome, and (b) whether peripheral blood IL-1β production by peripheral blood leukocytes is induced or primed, early after AIS." (PMID 17328808, 2007). "The post-stroke inflammatory response further reinforces this effect, as activated microglia, astrocytes, and infiltrating immune cells release cytokines—such as TNF-α, interleukin-1β (IL-1β), and S100 proteins—which are also implicated in pre-metastatic niche formation." (PMID 40909970, 2025). "Targeting the IL-1β–IL-1Ra–eicosanoids axis, for example, through agents such as anakinra, may offer potential benefits in controlling inflammation and promoting neuroprotection in stroke survivors." (PMID 41009650, 2025). "Importantly, by neutralizing IL-1β after stroke or blocking pro-inflammatory monocyte migration using a C-C chemokine receptor type 2 and 5 antagonist, post-stroke cardiac dysfunction could be prevented." (PMID 39592575, 2024). "Firstly, IL-1β is not only the core of inflammatory response in the brain after ischemic stroke, but also as a potential driver of innate immune memory, which may result in chronic post-stroke comorbidities, such as major vascular events." (PMID 39737165, 2024). "Importantly, endothelial inflammasome activation is a key factor in BBB disruption and endothelial cell death after stroke, which may be triggered by microglial secretion of IL-1β." (PMID 38550920, 2024). "For example, IL-1β induces delayed neuronal death by ferroptosis, a non-apoptotic type of cell death caused by iron-dependent reactive oxygen species accumulation after stroke." (PMID 39840011, 2024). "Additionally, the role of the AIM2 inflammasome was examined in stroke-induced cognitive impairment in elderly mice, which demonstrated that AIM2 mRNA and protein, combined with caspase-1, IL-1β, and IL-18, were enhanced in the hippocampus and cortex after stroke." (PMID 37450925, 2023). "Its exact mechanism of action on NLRP3 is unknown; however, its ability to effectively block NLRP3 activation and reduce the synthesis of the pro-inflammatory factor IL-1β has allowed its use for painful strokes and makes it a promising treatment option for stroke." (PMID 37165005, 2023). "Furthermore, experimental stroke induced a 4-fold up-regulation of IL-1α and 4.8-fold increase in IL-1β expressing NKCC1 KO microglia cells compared to WT animals, while the overall microglia density and the number of activated microglia were not different at 24-hour reperfusion." (PMID 35085235, 2022). "Therefore, IL-1β may be involved in the signaling cascade activated by AIM2 inflammasome, causing immune suppression and secondary infection after stroke injury." (PMID 35173738, 2022). "Colchicine could thus constitute a new and important treatment for secondary prevention after stroke, by targeting inflammation via pleiotropic actions, including the inhibition of interleukin-1β (IL1-β) and IL-6 synthesis, and the reduction of microtubule-dependent leucocyte motility and mitosis." (PMID 34300276, 2021). "Finally, we measured the expression of pro-IL-1β and IL-1β in perilesion regions in stroke brains." (PMID 34630845, 2021). "Importantly, depleting microglia induced a significant increase in the mRNA expression level of anti-inflammatory factors TGF-β1, Arg1, IL-10, IL-4, and Ym1 as well as a significant decline of pro-inflammatory factors TNF-α, iNOS, and IL-1β 3 days after stroke." (PMID 33757565, 2021).
Stroke (continued). "In particular, IL-1β has pleiotropic effects on the CNS, where the proinflammatory cytokine, released by neurons and glial cells, acts in an autocrine and/or paracrine fashion, participates in the onset and progression of different neurodegenerative diseases and stroke." (PMID 32377159, 2020). "To investigate whether the CD200/CD200R signaling pathway is involved in regulating microglia activation and inflammatory factor release after stroke in rats, we assessed microglia activation using immunofluorescence and inflammatory factor (such as Il-1β, Il-6, Tnf-α, Il-4, and Cd206) release." (PMID 32473633, 2020). "In addition, previous studies indicated that Prx1 could significantly induce the expression of TNF-α, IL-1β, and IL-6 via the Toll-like-receptor-4a-mediated NF-κB signaling pathway in stroke." (PMID 32317937, 2020). "Similarly, IL-1β levels are elevated in the CSF with peak levels at days 2 and 3 post-stroke." (PMID 31291966, 2019). "Furthermore, the levels of the inflammatory and anti-inflammatory cytokines such as IL-1β, IL-6, and IL-10, at the early stage of stroke might serve as important biomarkers to predict the prognosis for ischemic stroke patients." (PMID 30705764, 2019). "Thus, age might be an important intrinsic factor determining the level of microglia activation as well as the production of inflammatory cytokines such as IL-1β and IL-6 after stroke." (PMID 30705764, 2019). "In stroke models, adult progenitor cell therapy leads to decreased tissue levels of pro-inflammatory cytokines such as interleukin-1 alpha (IL1α), interleukin-1 beta (IL1β), and TNF-α and interleukin-6 (IL-6) and increased levels of anti-inflammatory cytokine such as IL-10." (PMID 29548333, 2018). "Sensing several stroke-induced stimuli, the cytosolic pattern recognition receptor NLRP3 recruits the adapter protein the apoptosis-associated speck-like (ASC) pro-caspase-1 leading to caspase-1 production and subsequent interlukin-1 β (IL-1β) maturation and release." (PMID 29654318, 2018). "After stroke, necrotic lesion produces abundant damage-associated molecular patterns (DAMPs), such as mitochondrial DNA, ATP, and carboxyalkylpyrroles, to which injured brain cells exposed secret inflammation mediators, such as platelet-activating factor (PAF), TNF-α and IL-1β, and chemokines." (PMID 27688603, 2016). "Literature suggests that IL-1β, the master regulator of inflammation, induces microglial activation and plays a crucial role in the progression of chronic neurodegenerative diseases such as AD and PD as well as acute neuroinflammatory conditions including stroke, ischemia, and brain injury." (PMID 26838598, 2016). "Enhanced IL-1β signal in SHRSP might be one of the factors contributing to stroke onset." (PMID 23326018, 2012). "Ferroptotic cell death releases DAMPs (damage‐associated molecular patterns), which stimulate microglial activation and inflammatory cytokine release (e.g., IL‐1β, TNF‐α), aggravating neuroinflammation and secondary neuronal injury post‐stroke." (PMID 41540791, 2026). "Systemic inflammation is a primary response following stroke and can be evaluated by measuring markedly upregulated pro-inflammatory cytokines, such as TNF-α, IL-6, and IL-1β." (PMID 41598337, 2026). "The levels of IL-1β and TNF-α are found to increase in the cerebrospinal fluid, peaking in the days following the stroke." (PMID 40364646, 2026). "Although the precise effects of YHJGs on AP-1 and NF-κB remain to be experimentally validated, the observed reduction in IL-1β, IL-6, and TNF-α suggests that YHJGs hold promise as a therapeutic agent for stroke-related inflammation." (PMID 41011203, 2025). "pronounced elevations in IL-1β, IL-6, TNF-α, MCP-1, and IFN-γ at day 1 post-stroke, exacerbated by bacterial injection." (PMID 40581646, 2025). "Following stroke, pro-inflammatory cytokines including TNF-α and IL-1β activate the Fas/FasL system, recruiting Fas-associated death domain (FADD) protein and procaspase-8." (PMID 41451361, 2025).
Stroke (continued). "On the contrary, IL-1β and TNF-α, which are upregulated in stroke tissue between 24 and 48 h after reperfusion and coincide with immune cell infiltration into the CNS, induce internalization and degradation of select BBB AJ and TJ proteins." (PMID 41024170, 2025). "TLR4 has been shown to be extensively involved in stroke, myocardial infarction and inflammation, where its binding to the bridging molecules MyD88 or MAPK activates NF-κB and triggers the up-regulation of IL-1β, IL-18 and TNF-α expression." (PMID 41143181, 2025). "The relationship between BB-DNA and plasma IL-1β levels was evaluated using linear regression, with age and sex, AF, IHD, CHF, CKD, stroke, neutrophil count, and eGFR included as covariates." (PMID 40724814, 2025). "After a stroke, P2X7 receptors on microglia are activated by ATP, triggering the release of IL-1β, IL-18, and TNF-α, promoting apoptosis and contributing to deep ion imbalance during neuronal death." (PMID 40289984, 2025). "The qPCR analysis showed that the mRNA levels of IL-6, IL-1β and TNF-α were increased in the stroke area." (PMID 40313968, 2025). "Here, we examined the mRNA expressions of IL-1β, IL-6 and TNF-α after 7 d of stroke, which are crucial for the cerebral ischemia-induced neuroinflammatory process." (PMID 40004043, 2025). "Ginkgolide (GDL) treatment inhibits astrocyte activation and the expression of IL-1β and TNF-α, enhances cell viability, and reduces peri-scar astrocyte reactivity, creating favorable conditions for post-stroke recovery." (PMID 41450734, 2025). "During acute phases of stroke, IL-17A is involved in microglial activation and neuroinflammation, promoting the expression of TNF-α, IL-1β, and other inflammatory factors and downstream signaling molecule NF-κB p65." (PMID 40289984, 2025). "Our research also revealed that in the classic tMCAO stroke model, the levels of TNF-α and IL-1β, two of the five core target genes, increased significantly." (PMID 41471340, 2025). "Serum IL-1β and IFN-γ were elevated in all four phases following stroke onset while IL-4 was elevated exclusively in the recovery phase (48-96 h) (p<0.05)." (PMID 38870172, 2024). "For example, in conditions like multiple sclerosis or stroke, the peripheral levels of cytokines such as interleukin-6 (IL-6), tumor necrosis factor-alpha (TNF-α), and interleukin-1 beta (IL-1β) have been found to be elevated." (PMID 38285083, 2024). "As important cytokines in vivo, IL1β, and IL18 play important roles in the progression and prognosis of many neurological diseases, including stroke and glioma." (PMID 38405399, 2024). "The levels of MPO-DNA, PAD4, C1q, IL-1β, IL-6, IL-8 and HMGB1 change significantly over time during the acute phase of stroke (all P < 0.05)." (PMID 39737165, 2024). "After a stroke, mitochondria govern the NLRP3 inflammasome by discharging molecular contents, which release pro-inflammatory cytokines such as IL-1β and IL-18, driving the inflammatory response, potentially linked to post-stroke depressive-like behaviors." (PMID 38377025, 2024). "Elevated levels of cytokines, including IL-1β, TNF-α, and IL-6, in the bloodstream of stroke patients imply a higher likelihood of deterioration of their condition." (PMID 38742047, 2024). "We reanalyzed plasma IL-1β, IL-6, TNF-α, sICAM-1, sVCAM-1, and FKN levels data obtained in a previous study to test potential differences between HGS stroke patients (within 7 days or 1-year from stroke onset) and healthy controls." (PMID 36536168, 2024). "We compared the efficacy of the three treatment outcomes by analyzing the National Institutes of Health Stroke Scale (NIHSS) scores, and the levels of serum inflammatory factors (IL-8, TNF-α, and IL-1β), cone like protein-1 (VILIP-1), and caveolin-1 (Cav-1)." (PMID 38827855, 2024). "Gene floxed females showed more robust expression of CD68 in microglia, elevated brain and plasma levels of IL-1β or TNF-α, after stroke." (PMID 39399684, 2024).
Stroke (continued). "Kdm6afl/fl mice had significantly higher plasma levels of IL-1β than fl/y mice; whereas Kdm5cfl/fl mice had higher levels of TNF-α than either fl/y and CKO mice after stroke." (PMID 39399684, 2024). "Lower serum GPR37 levels and higher levels of inflammatory markers such as S100β, neuron-specific enolase (NSE), IL-1β, and TNF-α are observed in stroke patients compared to healthy controls." (PMID 39633709, 2024). "Cytokines released during stroke, such as TNF-α, IL-1β, and IL-6, further activate the inflammatory response and induce cell death." (PMID 38742047, 2024). "A significant increase in IL-1β levels was observed in HGS stroke patients compared to healthy controls, an effect that was maintained 1-year after stroke." (PMID 36536168, 2024). "Genes related to inflammation such as Ccl5, Cxcl5, Il1a, Tnfsf10, Nfkb1, Tnfrsf1b, Ccr7, Tnfrsf9, Ccl7, Il1b, Il6, and Ccl24 were also downregulated upon MMP-3 KO in male stroke brains." (PMID 39000490, 2024). "At the molecular level, we observed that diminished Nrf2/HO-1 axis activation in MG resulted in increased CD68/IL-1β and suppressed CD206 expression in MG, leading to the elevated inflammatory MG in MG-specific Nrf2 knockdown stroke mice." (PMID 39469715, 2024). "Neuroinflammation is an important pathogenic factor in cerebral ischemia–reperfusion, and it has been reported that stroke activates the expression of pro-inflammatory cytokines, such as TNF and IL-1β." (PMID 37630972, 2023). "Stress in stroke stimulates peripheral immune cells to secrete pro-inflammatory cytokines, TNF-α, IL-1β and IL-6, which can cross the BBB and further activate microglia and astrocytes in the CNS to secrete more pro-inflammatory cytokines." (PMID 37199575, 2023). "Consistent with previous studies, the dramatic increase in stroke-induced inflammatory cytokines TNF-α, IL-1β, and IL-6 was suppressed after treatment with NSC-EV." (PMID 37691119, 2023). "In the early stage post-stroke, pro-inflammatory microglia can induce the destruction of gap junctions and increase the permeability of hemichannels by secreting TNF-α and IL-1β." (PMID 37464832, 2023). "In this study were analysed glutamate, IL-1β, IL-6, IL-10 and TNF-α according to the time of stroke." (PMID 36835156, 2023). "Three major pro-inflammatory cytokines—IL-1β, TNF-α, and IL-6—both mediate and aggravate the inflammatory response following stroke." (PMID 38102677, 2023). "The main specific targets proposed for stroke therapies are the cytokines TNF-α, IL-1β, and IL-6, and the adhesion molecule ICAM-1, which will be discussed in this section." (PMID 37762627, 2023). "This suggests that plasma IL-1β levels in combination with TCD measurements may be used to improve evaluation of stroke risk in HbSS patients, by early identification of those needing intensive prophylactic interventions, especially as these strokes can be asymptomatic or silent." (PMID 36969226, 2023). "In T2DM mice, stroke induced earlier and higher TLR4, NLRP3, and cytokine expression (SAA, IL1β, IL6, TNFα) in the liver compared to heart and kidney, as measured by Western blot." (PMID 36968490, 2023). "In the present study, we demonstrated that THSWD attenuated mitochondrial DNA and nuclear DNA damage during stroke; reduced AIM2, NLRC4, and Caspase-1 inflammasomes; and inhibited IL-1β and IL-18 inflammatory factor release after IS." (PMID 36034843, 2022). "In stroke patients, rehabilitative 4-week treatment with ELF-EMF (F = 40 Hz, Bm = 5 mT), in combination with physiotherapy, reduced both IL-1β plasma and IL-1β mRNA expression levels and increased IL-2 plasma levels without any adverse effects." (PMID 35203533, 2022). "Peripheral inflammatory factors, including IL‐1β and TNF‐α, are more likely to aggravate BBB damage and even worsen stroke outcomes." (PMID 35322553, 2022). "There was also a decrease in the release of IL-1β and TNF-α from co-cultures involving monocytes from stroke patients (p < 0.05)." (PMID 36277912, 2022).
Stroke (continued). "On the other hand, IFN-γ, IL-1β, and TNF-α showed reduced secretions in Mφ-MSC co-cultures involving stroke patient derived Mφ, as compared to healthy control derived Mφ." (PMID 36277912, 2022). "The current study, therefore, investigated the associations between SNPs of inflammatory molecules, consisting of IL-1β, TNF-α, IL-6, IL-10, IL-18, interferon-γ (IFN-γ) and C-reactive protein (CRP), and PSD at 2 weeks after stroke (early-onset PSD)." (PMID 36225923, 2022). "Interleukin-1β (IL-1β), tumor necrosis factor-α (TNF-α) and IL-6, are the main inflammatory factors that trigger and exacerbate the inflammatory response after stroke." (PMID 35281064, 2022). "Real-time quantitative PCR measurements suggested the prominent elevation of multiple pro-inflammatory cytokines and chemokines, including IL-1β, IL-6, TNF-α, CCL2, CXCL1, and CXCL10 after stroke." (PMID 35761277, 2022). "There was also a statistically significant decrease in the release of IL-6, IL-1β, and TNF-α from trans-well co-cultures of MSCs with stroke derived monocytes as compared to co-cultures using healthy monocytes (p < 0.05)." (PMID 36277912, 2022). "Stroke-induced cytokines (IL-6, TNF-α, and IL-1β) and MCP-1 and CCR2 mRNA levels were significantly higher in the diabetic brain compared to control at 1 day after MCAO, and this increased expression was sustained until 3 days post-stroke." (PMID 35784349, 2022). "IL-1β and TNF-α play a key role in the neuroimmune development of stroke by promoting neurotoxicity and the development of harmful inflammation after cerebral ischemia." (PMID 35469165, 2022). "Canakinumab is a fully human monoclonal antibody that inhibits IL-1β and has been shown to reduce CRP levels and the composite of death, myocardial infarction, or stroke." (PMID 36620625, 2022). "The maturation of IL-1β depends on inflammasomes, among which NLRP3-containing inflammasome is the best-studied inflammasome in the scope of stroke." (PMID 34628598, 2022). "In trans-well co-cultures of MSCs and monocytes isolated from stroke patients, we found statistically significant increased levels of IL-4 and MCP-1, and decreased levels of IL-6, IL-1β, and TNF-α." (PMID 36277912, 2022). "Similar to our current study, recent studies have indicated that after stroke, miR-223 can downregulate NLRP3 to negatively regulate caspase-1 and IL-1β to suppress neuroinflammation." (PMID 34408803, 2021). "Post-stroke inflammasome activation, especially NLRP3, cleaved Caspase-1, cleaved Caspase-11, IL-1β, IL-18, and GSDMD, peaked at 3–5 days and declined at 7 days with the participation of multiple components in mice." (PMID 33967935, 2021). "Depletion of IL-1α or IL-1β attenuated BBB disruption and decreased infarct size in experimental stroke." (PMID 34248961, 2021). "Omega-3 polyunsaturated fatty acids prevent the release of cyclooxygenase 2, hypoxia-inducible factor 1α, and IL-1β, as well as the activation of NOS, thereby having therapeutic potential in stroke." (PMID 35008440, 2021). "The cytokines IL-1β and TNF-α play an important role in regulating immune responses after ischemic stroke and are stroke potential therapeutic targets." (PMID 34898370, 2021). "In summary, in Wistar rats, IL-1β, IL-6, TGF-β, BDNF/TrkB and VEGF levels were increased at 24-h after stroke, IL-10 was increased at 30 days." (PMID 34408211, 2021). "They reported that both activated and naïve MSCs induced complete behavioral recovery, reduced infarct volumes, and reduced microglial activation and levels of IL-1β, TNF-α, and IL-6 in treated animals, compared with vehicle-treated control stroke animals." (PMID 32862401, 2021). "At 1 day after stroke, macrophages took up the highest part of NLRP3+ (N: 15.26 ± 13.31%; DC: 4.75 ± 4.90%; M: 38.74 ± 25.65%, P < 0.001) or IL-1β+ (N: 21.80 ± 20.52; DC: 5.27 ± 4.13; M: 47.36 ± 29.30, P < 0.001) cells in patients' blood." (PMID 33967935, 2021).